HIP1R (huntingtin interacting protein 1 related)
Diseases named in the same sentence as HIP1R in open-access papers (continued):
Sharing a sentence is not in itself a finding about the gene and the disease.
thyroid cancer (continued). "The role of HIP1R and HIP1R-induced endocytosis in thyroid cancer, however, has not been reported." (PMID 35209947, 2022). "The mechanism that flurbiprofen disturbs the interaction between HIP1R and PTEN in thyroid cancer cells has not been explored." (PMID 35209947, 2022).
tumor (19 papers, 2019 to 2026). "In another study, HIP1R deficiency in tumor cells led to the inhibition of selective autophagy degradation of PDL1, which in turn promoted immune escape." (PMID 38001512, 2023). "Deficiency of HIP1R in tumor cells was demonstrated to cause PD-L1 accumulation and suppressed T-cell-mediated cytotoxicity." (PMID 37443736, 2023). "LAMA2, MAP1B, and HIP1R were among the genes with higher mutation frequencies (8%, 6%, and 5%, respectively), suggesting these mutations play a crucial part in tumor initiation and progression, and these genes could be potential driver genes or therapeutic targets." (PMID 40589759, 2025). "Based on this mechanism, a fusion peptide named PD-LYSO—comprising the PD-L1-binding domain (Q776–Q807) and the lysosomal sorting signal (M966–Q979) of HIP1R—has been designed to efficiently reduce PD-L1 expression in tumor cells." (PMID 41592073, 2026). "TRAPPC4, HIP1R, and PTMs orchestrate the dynamic regulation of PD-L1, enabling tumor cells to fine-tune their expression and sustain immune suppression." (PMID 40507229, 2025). "Experimental validation showed that knockdown of the HIP1R gene significantly reduced tumor cell expression, confirming its critical role in tumor development." (PMID 40589759, 2025). "HIP1R, a protein involved in endocytosis and cellular trafficking, has been reported as a tumor inhibitor in various types of cells." (PMID 40992658, 2025). "Depleting HIP1R leads to the accumulation of PD-L1 at the plasma membrane, further suppressing T-cell activity and enabling tumor cells to evade immune destruction." (PMID 40507229, 2025). "The investigation demonstrates that HIP1R inactivation in multiple cancer cell lineages promotes PD-L1 accumulation, augmenting its cell surface expression and attenuating T-cell-mediated tumor cytotoxicity effectiveness." (PMID 40507229, 2025). "Taken together, these data indicate that HIP1R functions as a tumour suppressor to negatively regulate the malignancy of PAAD cells." (PMID 36811277, 2023). "HIP1R actually targets PD-L1 for lysosomal degradation, inhibiting tumor growth by increasing T cell cytotoxicity." (PMID 37443736, 2023). "To validate the tumour suppressor role of HIP1R, we constructed pcDNA3.1‐HIP1R expression vector to overexpress HIP1R in PAAD cells." (PMID 36811277, 2023). "In summary, this study demonstrated that HIP1R acts as a tumour suppressor which is downregulated in PAAD tissues and cells, and its reduced expression predicts a poor prognosis in PADD patients." (PMID 36811277, 2023). "In contrast, HIP1R in tumor cells can induce the autophagic degradation of PD-L1 and enhance T-cell toxicity to tumor cells." (PMID 37398678, 2023). "We cannot conduct additional experiments for mRNA testing of HIP1R and PD-L1, because very little tumor tissue remains in paraffin tissue." (PMID 32403421, 2020). "The results revealed that HIP1R mRNA and protein levels were downregulated in primary GC tissues (mRNA: adjacent 34.12 ± 17.013 vs tumor 20.99 ± 12.371, P < .001; Protein: adjacent 3.33 ± 0.200 vs tumor 2.99 ± 0.211, P < .001)." (PMID 32548851, 2020). "The expression levels of HIP1R were tested by the transcriptional and translational expression analysis and immunohistochemistry (IHC) in matched adjacent non‐tumorous vs tumor tissue specimens." (PMID 32548851, 2020). "In 380 matched adjacent non‐tumorous tissues and corresponding tumor tissues, 352 of 380 (93%) adjacent non‐tumorous gastric mucosa samples showed HIP1R high expression." (PMID 32548851, 2020). "A designed peptide (PD-LYSO) that combines PD-L1–binding sequence of HIP1R and lysosome-sorting signal can effectively deplete the PD-L1 expression on the surface of tumor cells." (PMID 32850400, 2020). "HIP1 has been reported to affect tumorigenesis in many tumor types;17, 18, 19, 20, 21 however, HIP1R has rarely been reported on in tumors." (PMID 32548851, 2020).
tumor (continued). "Our previous studies have shown that depletion of huntingtin-interacting protein 1-related protein (HIP1R) in tumor cells leads to significant upregulation of PD-L1, thus resulting in the suppression of T cell cytotoxicity." (PMID 32944392, 2020). "The peptide PD-LYSO successfully targets PD-L1 expressed by tumor cells to lysosomes for degradation, taking the place of the depleted HIP1R." (PMID 31647023, 2019). "Recent studies have found that tumor cells have the potential to control the molecular mechanism (depletion of HIP1R) of lysosomal degradation of PD-L1, leading to its intracellular accumulation and inducing immune tolerance." (PMID 31647023, 2019). "Moreover, Huntington-interacting protein 1-related (HIP1R) facilitates the lysosomal trafficking and degradation of PD-L1, thereby promoting T cell-mediated tumor killing." (PMID 41592073, 2026). "In GC cancer, HIP1R has been shown to inhibit tumor progression." (PMID 40992658, 2025). "Together, these data indicate that HIP1R may act as a tumour suppressor which is downregulated in PAAD tissues and cells." (PMID 36811277, 2023). "Thus, tumor cells with high expression of HIP1R presented lower PD-L1 level and poor response to the therapy targeting PD-1/PD-L1 signal." (PMID 37031178, 2023). "In this study, we showed the downregulation of HIP1R in PAAD tissues and cell lines, and demonstrated that HIP1R serves as a tumour suppressor in PAAD since the overexpression of HIP1R suppressed the proliferation, migration and invasion, and induced apoptosis in PAAD cells." (PMID 36811277, 2023). "Interestingly, the authors found that HIP1R was negatively correlated with PD-L1 level and served as an independent predictor for tumor response to the anti-PD-1 treatment." (PMID 37031178, 2023). "The tumor-suppressing effect of HIP1R has also been reported." (PMID 35209947, 2022). "A study showed that huntingtin interacting protein 1 related protein (HIP1R) targets PD-L1 to lysosomal degradation to change cytotoxicity mediated by T cells, but inactivation of HIP1R in tumor cells caused the expression of PD-L1 and inhibitory cytotoxicity mediated by T cells." (PMID 32850400, 2020). "Consistent with this, Wang et al23 found that disruption of HIP1R could inhibit tumor cell sensitivity to T cell killing and lead to decreased tumor cell apoptosis." (PMID 32548851, 2020). "Our study implicates that HIP1R acts as a tumor suppressor gene promoting GC cell apoptosis." (PMID 32548851, 2020). "Based on the previous findings, we speculated that HIP1R may alter the downstream signaling pathways of cells/growth factor receptors by promoting their endocytosis, thus stimulating the proliferative capacity of tumor cells." (PMID 35209947, 2022). "Mechanistically, HSD17B12 boosts anti-tumor immunity by facilitating VAC14-ESCRT-mediated degradation of PD-L1, independently of CMTM6, HIP1R, and palmitoylation." (PMID 41592073, 2026). "Nevertheless, splicing defects and disrupted protein levels were also observed for multiple tumor suppressor genes, including OGFR and HIP1R (Huntingtin Interacting Protein 1-related), two factors known to suppress cell proliferation." (PMID 41290606, 2025). "The intricate regulatory roles of DRG2, TRAPPC4, HIP1R, and CMTM6 in PD-L1 trafficking and stability present compelling opportunities for therapeutic intervention to enhance anti-tumor immunity." (PMID 40507229, 2025). "Chi‐square test showed that low HIP1R expression was significantly correlated with more advanced TNM stages, larger tumour sizes and more lymph node metastasis." (PMID 36811277, 2023). "Thus, we speculate that HIP1R may act as a tumor suppressor for GC development." (PMID 32548851, 2020). "The results showed that patients with a high proportion of HIP1R+, CDKN2A+, and IDHR132H+ tumor cells had a significantly better prognosis than those with a low proportion of positive tumor cells, while a high proportion of EGFR+ tumor cells was associated with a poor prognosis." (PMID 40264576, 2025).
tumor (continued). "On the basis of the ‘binding–sorting’ model derived from the molecular roles of HIP1R, we have rationally designed the peptide PD-LYSO, incorporating the lysosome-sorting signal and the PD-L1-binding sequence of HIP1R, and used it to successfully deplete PD-L1 expression in tumor cells." (PMID 32944392, 2020).
cancer (9 papers, 2020 to 2025). A tumor composed of atypical neoplastic, often pleomorphic cells that invade other tissues. "But inside many cancer cells the HIP1R gene has been altered, which in turn causes PD-L1 molecules to be overexpressed and presented in high abundance on the cancer cell surface, leading to the immune cells inhibition, especially T cells anergy." (PMID 35269988, 2022). "Although cancer cell exhibits immune evasion by abnormal expression of PD-L1, deficiency of HIP1R in cancer cells increases PD-L1 protein levels." (PMID 34493296, 2021). "Although HIP1R associates with human cancer biology, its precise role in GC progression remains unclear." (PMID 32548851, 2020). "HIP1R is a new gene implicated in RA FLS invasiveness and migration, and regulates unique pathways and cell processes relevant to both RA as well as cancer biology." (PMID 40214437, 2025). "Only recently has HIP1R attracted attention in cancer research, so few studies have been done on HIP1R." (PMID 32403421, 2020). "It is still important to thoroughly understand the molecular mechanisms by which HIP1R regulates its differential biological effects in GC and other cancer types." (PMID 32548851, 2020). "Conversely, overexpressing HIP1R results in decreased levels of PD-L1, indicating that HIP1R could be a potential therapeutic target for modulating immune evasion in cancer." (PMID 40507229, 2025). "HIP1R contains a lysosomal targeted signal and binds to PD-L1, which subsequently delivers PD-L1 into lysosomes for autophagic degradation and enhances T cell killing of cancer cells." (PMID 33159034, 2020). "In this study, it shows that HIP1R acts as a autophagy receptor for PD-L1 binding and induces PD-L1 selective autophagic degradation in lysosome, subsequently, inhibits tumor growth by increasing T cell cytotoxicity, suggesting that autophagic degradation of PD-L1 suppresses cancer immune escape." (PMID 34493296, 2021). "Therefore, we speculate that HIP1R expression has properties to inhibit cancer cell migration and invasion." (PMID 32548851, 2020). "The most significantly DEGs in both HIP1R and HIP1 analyses are involved in cancer cell behaviors and outcomes." (PMID 40214437, 2025). "The strategic inhibition of multiple factors—DRG2, TRAPPC4, HIP1R, and CMTM6—represents a compelling approach to regulate PD-L1 surface levels on cancer cells, potentially reversing immune resistance mechanisms and amplifying the effectiveness of PD-1/PD-L1 blockade strategies." (PMID 40507229, 2025).
adenocarcinoma (1 paper, 2020). A common cancer characterized by the presence of malignant glandular cells. "The group with high HIP1R mRNA expression exhibited poorer OS in patients with adenocarcinoma (p = 0.026)." (PMID 32403421, 2020).
HIP1R also shares sentences with these, for which no sentence is quoted: bladder cancer (2 papers); Arrhythmia (1); gastric tumor (1); metastatic prostate carcinoma (1); neurological disorders (1); rheumatoid arthritis (1); schizophrenia (1).